PLK1 (polo like kinase 1)
Diseases named in the same sentence as PLK1 in open-access papers (continued):
Sharing a sentence is not in itself a finding about the gene and the disease.
melanoma (continued). "The Kaplan-Meier survival curve showed that the expression of PLK1 and NUMB (isoforms 1-4) were inversely associated with survival of melanoma patients as high PLK1 with low NUMB showed significant decrease in OS compared to low PLK1 and high NUMB." (PMID 38184733, 2024). "PLK1 is a critical cell cycle regulatory protein of the serine/threonine kinase family, closely related to melanoma development and growth." (PMID 39353904, 2024). "In this study, we were able to demonstrate that shRNA-mediated inhibition of PLK1 in the melanoma cell lines (A375 and SK-MEL-2) inhibited the NOTCH pathway by decreasing the expression of NICD (NOTCH intracellular domain), as well as its nuclear intensity." (PMID 38184733, 2024). "In fact, several studies, including those from our laboratory, have shown that PLK1 is significantly overexpressed in several cancers, including melanoma (reviewed in3)." (PMID 38184733, 2024). "Previously, we have also demonstrated an association of PLK1 with NUMB6, although it is not fully known how the two proteins interact with each other during melanoma progression." (PMID 38184733, 2024). "To further experimentally validate the effects of PLK1 on the cellular migration of melanoma cells, we performed wound healing and Matrigel invasion assays." (PMID 38184733, 2024). "For example, a novel LNP system encapsulating CRISPR/Cas9 was designed for targeting the PLK-1 gene in melanoma cells." (PMID 38607007, 2024). "Using multiple PLK1-modulated melanoma cell lines, we found that PLK1 is involved in the regulation of cell migration, invasion, and EMT via its kinase activity and NOTCH activation." (PMID 38184733, 2024). "In summary, our study provides mechanistic evidence using multiple human melanoma cell line models and clinical patient tissues that PLK1 is an important regulator of EMT, cell migration, and invasion, and thus, melanoma progression." (PMID 38184733, 2024). "Employing autophagy inhibitors or NOD2 overexpression in conjunction with autophagy inhibitors effectively curtailed melanoma progression, potentially serving as a mechanism by which TYMS and PLK1 influence melanoma." (PMID 39353904, 2024). "In the next series of experiments, we determined the effects of forced overexpression of PLK1 on melanoma cell proliferation, migration, invasion and EMT markers." (PMID 38184733, 2024). "Melanoma cells with constitutively kinase-active PLK1 showed higher proliferation, migration, and invasion potential, as well as modulation in EMT markers compared to the kinase-inactive PLK1 expressing cells." (PMID 38184733, 2024). "In an earlier study from our lab, we have shown that PLK1 knockdown in A375 melanoma cells reduced growth and altered metabolic regulation." (PMID 38184733, 2024). "Previous studies describe synergistic anti-tumor activity by combining the inhibition of PLK1 and NOTCH in melanoma or PLK1 and MEK in NRAS-mutated melanoma." (PMID 36768289, 2023). "Subsequently, when we inhibited PLK1, we found decreased cell viability of melanoma cells resistant to BRAFi." (PMID 36768289, 2023). "Overexpression of the AURKA/B and PLK1 in melanoma has been correlated with poorer survival prospects." (PMID 37259298, 2023). "Treatment of various BRAF-mutated melanoma cell lines with the BRAF inhibitor dabrafenib (GSE98314) reduced the expression of EZH2 and PLK1 in a comparable manner." (PMID 36768289, 2023). "Since AURK A/B and PLK1 are overexpressed in many cancer types, including melanoma, and considering that these serine/threonine mitotic kinases are currently regarded as attractive anticancer targets, 3a represents a promising pre-clinical drug prototype." (PMID 37259298, 2023). "This is also supported by our in silico findings (GSE50509), which show comparable expression levels of PLK1 in progressive melanomas during treatment with BRAF inhibitors compared to the time before treatment." (PMID 36768289, 2023).
melanoma (continued). "Analysis of melanoma patients with PLK1 in the TCGA database showed that high mRNA levels were associated with worse survival." (PMID 36836481, 2023). "When we inhibited both BRAF and PLK1, we achieved an improved response of BRAFi-resistant melanoma cells, which was comparable to the combined inhibition of BRAF and EZH2." (PMID 36768289, 2023). "PLK1 is highly expressed in various tumors, including lung, head and neck, esophageal, gastric, melanoma, breast, ovarian, endometrial, colorectal, glioma, renal cell carcinoma, and thyroid cancer." (PMID 36675706, 2022). "Plk1 overexpression has been identified in many cancers and Plk1 expression was increased in melanoma and metastatic melanoma compared to benign nevi." (PMID 35326726, 2022). "Plk1 inhibition with Volasertib was successful at low concentrations similar to our study in melanoma cell lines in vitro with growth inhibition." (PMID 35326726, 2022). "The polo-like kinase 1 (PLK1), which is required for mitotic entry and centrosome maturation in late G2 phase/early prophase, is overexpressed in NRASmut melanoma." (PMID 36551302, 2022). "Plk1 mRNA levels are high in kidney, lung, breast, ovarian, colon cancers, melanoma and particularly in HNSCC." (PMID 34646387, 2021). "Genes positively or negatively correlated with PLK1 were mainly assembled in pathways such as DNA replication, cell cycle, mismatch repair, Ras signaling pathway, melanoma, EGFR tyrosine kinase inhibitor resistance and homologous recombination (P < 0.05)." (PMID 33354424, 2020). "Volasertib and Rigosertib targeting Plk1 are 2 promising inhibitors inducing cell cycle arrest and apoptosis, which are in clinical trials for different cancer entities, except melanoma." (PMID 30728057, 2019). "PLK1 has been found to be upregulated in many tumor types including: melanoma, non-small-cell lung, prostate, and colorectal and overexpression of Plk1 correlates with a poor clinical prognosis." (PMID 29402316, 2018). "This strategy is utilized to treat melanoma by designing sgRNA targeting Polo‐like kinase‐1 (Plk1) of the tumor." (PMID 29201613, 2017). "Our results are consistent with previous studies that suggested pro-migratory activity of PLK1 in colorectal, breast, thyroid cancer, and melanoma." (PMID 27003818, 2016). "PLK1 inhibitors appear to be versatile anticancer agents for a variety of cancers, and their recent interplay with immunotherapies will likely open interesting research avenues for melanoma treatment." (PMID 39658088, 2025). "According to our prior observations that the PLK1/BACH1 axis contributes to the Vemurafenib resistance in melanoma, we investigated whether the PLK1 inhibitor Volasertib, in combination with Vemurafenib, could achieve improved therapeutic efficacy in melanoma." (PMID 41284701, 2025). "Of note, ample evidence indicates that elevated Plk1 expression promotes metastasis in mouse melanoma, characterized by the migration of numerous cells through muscular tissue and the increased presence of pigmented metastatic sites in the draining lymph nodes." (PMID 41284701, 2025). "In line with our hypothesis that mitochondrial determinants are linked to this resistance, we next identified 124 transcripts encoding mitochondrial proteins that significantly correlate with the sensitivity to PLK1 targeting in melanoma cells." (PMID 39658088, 2025). "Importantly, the knockdown of BACH1 abolished the phenotypes elicited by PLK1 in both human and melanoma cells, with reduced glycolysis, increased OXPHOS, inhibited metastasis, and resensitization to Vemurafenib treatment." (PMID 41284701, 2025). "Besides, both mouse and human melanoma cells exhibited a similar pattern of decreased cellular general oxidative stress with overexpressed PLK1." (PMID 41284701, 2025).
melanoma (continued). "PLK1 overexpression contributed to drug resistance in mouse melanoma cells." (PMID 41284701, 2025). "Similarly, upon Hemin treatment, an inducer of BACH1 degradation, PLK1 overexpression led to more stabilized BACH1 in the melanoma cells." (PMID 41284701, 2025). "Importantly, overexpression of PLK1 promoted the Warburg effect, metastasis, and Vemurafenib resistance in human and mouse melanoma cells." (PMID 41284701, 2025). "However, the role of PLK1 in melanoma metastasis and metabolism is elusive and requires further investigation." (PMID 41284701, 2025). "Taken together, our findings pointed out that PLK1 may contribute to melanoma progression and be correlated with poorer patient survival." (PMID 41284701, 2025). "Consistent with our in vitro findings, increased PLK1 expression could enhance metastatic capability of mouse and human melanoma cells in vivo, leading to increased metastatic loci in lung tissues after intravenous inoculation." (PMID 41284701, 2025). "To identify the role of PLK1 in melanoma, we analyzed patient data from the TCGA database." (PMID 41284701, 2025). "Taken together, these analyses show that mitochondrial signatures are associated with distinct responses to RSK and PLK1 inhibitors and that targeting specific mitochondrial proteins is a valid approach to fine-tune the sensitivity of melanoma cells to PLK1 inhibition." (PMID 39658088, 2025). "Besides, a robust elevation of PLK1 expression was observed in primary melanoma tissues, in comparison to the benign melanocytic nevus." (PMID 41284701, 2025). "NOD2 acts by regulating the TYMS/PLK1 signaling axis in melanoma." (PMID 39353904, 2024). "Overall, our research highlights the protective role of NOD2 in melanoma and suggests that targeting NOD2 and the TYMS/PLK1 signaling axis is a high-profile therapy that could be a prospect for melanoma treatment." (PMID 39353904, 2024). "As EMT has been considered a major determinant of melanoma metastasis, our study suggests a potential role of PLK1, NUMB, and NOTCH in the metastatic progression of melanoma that might be associated with poor survival of patients." (PMID 38184733, 2024). "Since PLK1 is a direct cell cycle checkpoint, we hypothesized that the regulation of melanoma cell behavior by NOD2 depends on changes in PLK1." (PMID 39353904, 2024). "Furthermore, NOD2 overexpression in combination with TYMS inhibition and combination therapy targeting TYMS and PLK1 showed synergistic inhibition of melanoma proliferation and migration." (PMID 39353904, 2024). "Additionally, PLK1 and NUMB expressions were inversely associated with melanoma patient survival as high PLK1 with low NUMB (all isoforms 1-4) showed a significant decrease in patient survival compared to low PLK1 and high NUMB." (PMID 38184733, 2024). "Further, melanoma patients with high PLK1, and high NOTCH expression could be a candidate for combined targeting of PLK1 and NOTCH." (PMID 38184733, 2024). "We hypothesized that NOD2 may influence chemoresistance in melanoma through the TYMS/PLK1 signaling axis." (PMID 39353904, 2024). "Also, the significance of implementing NOD2 and the TYMS/PLK1 signaling axis was evaluated as targets for therapeutic intervention in melanoma." (PMID 39353904, 2024). "We further asked if PLK1 has the ability to activate NOTCH in melanoma cells." (PMID 38184733, 2024). "Additionally, we performed immunofluorescence analysis of EMT markers E-cadherin and N-cadherin after PLK1 knockdown in melanoma cells." (PMID 38184733, 2024). "NOD2 suppresses melanoma development by inhibiting the TYMS/PLK1 signaling axis." (PMID 39353904, 2024). "Simple Western analysis was performed to confirm PLK1 overexpression in melanoma cells and its effect on EMT markers, which showed an increasing trend in the expression of mesenchymal markers, such as N-cadherin and Vimentin, as well as transcription factors ZEB1 and SNAIL." (PMID 38184733, 2024).
melanoma (continued). "The TMA was co-immunostained for PLK1, N-cadherin, E-cadherin, and the melanoma biomarker S100." (PMID 38184733, 2024). "PLK1 is a major regulator of mitosis and cytoskeletal dynamics and is associated with poor prognosis and metastasis in a range of cancers including HCC, non-small cell lung cancer, breast, ovarian, squamous cell carcinomas, melanoma, and large B cell lymphoma." (PMID 37648284, 2023). "Because we revealed that PLK1 is downregulated by vemurafenib in sensitive melanoma cells markedly stronger than in resistant cells, we hypothesize that PLK1 may be an important factor in resistance to vemurafenib." (PMID 36768289, 2023). "Because we have shown that a high PLK1 expression is associated with the occurrence of resistance and worse patient outcomes, we wondered whether PLK1 inhibition affects melanoma cell viability." (PMID 36768289, 2023). "Thus, the combination of BRAF inhibitors with inhibitors against EZH2 or against downstream targets of EZH2, such as PLK1, represent new therapeutic options for melanoma." (PMID 36768289, 2023). "Knockdown of PLK1 resulted in significantly reduced viability and growth of melanoma cells." (PMID 35610275, 2022). "In addition, knockdown of PLK1 resulted in decreased clonal survival, cell cycle arrest, and apoptosis in melanoma cells." (PMID 35610275, 2022). "PLK1 was shown to be overexpressed in melanoma and its therapeutic targeting could be beneficial in various types of cancer." (PMID 35559262, 2022). "The MEK/PLK1 inhibitor combination might deserve to be further tested in patients with NRAS-driven melanoma." (PMID 36551302, 2022). "The in vivo cancer Plk1 genome‐editing induced ≈75% suppression of the melanoma progression." (PMID 29201613, 2017). "A chemogenomic screen coupling PLK1 inhibition and genome-wide gene knockout in melanoma cells could be useful to precisely identify sensitization or desensitization factors that could explain therapeutic resistance or help better position PLK1 inhibitors." (PMID 39658088, 2025). "Additionally, it has been reported that PLK1 inhibitor could synergize with MEK inhibitor in NRAS mutant melanoma." (PMID 41284701, 2025). "These analyses suggest that the antiproliferative and pro-inflammatory effects of RSK inhibitors, such as BI-D1870, BRD7389, PMD-026, AF007, and fisetin in previous melanoma studies could be due to the unselective targeting of other kinases, such as PLK1." (PMID 39658088, 2025). "Thus, the effects of PLK1 on EMT in melanoma could be mediated through the NOTCH pathway, which is shown to stimulate the EMT process in other cancers." (PMID 38184733, 2024). "In addition, we investigated the impact of PLK1 expression on the survival of melanoma patients." (PMID 36768289, 2023). "Furthermore, our previous demonstration of PLK-1 as a potential therapeutic target in melanoma, together with the ability of PLK-1 inhibition to override MITF-mediated intrinsic resistance suggest mitotic kinases as potential avenues for therapeutic intervention in melanoma." (PMID 26962685, 2016). "To investigate the regulatory role of PLK1 on BACH1 in melanoma, we assessed the protein stability of BACH1 and found its protein level significantly reduced in melanoma cells under the PLK1 inhibition." (PMID 41284701, 2025). "Thus, we hypothesized that the antiproliferative effects of several RSK inhibitors might be caused by off-target inhibition of other protein kinases, such as PLK1, a master regulator of cell division and candidate for targeted therapy with increased expression in melanoma." (PMID 39658088, 2025).
melanoma (continued). "Our results showed that melanoma cells with higher PLK1 expression contributed to increased ratio of NADPH/NADP+ and GSH/GSSG in mouse and human melanoma cells, suggesting the induction of antioxidant ability." (PMID 41284701, 2025). "Our data provide evidence that PLK1 plays an important role in cell migration, invasion, and EMT in melanoma." (PMID 38184733, 2024). "We found that inhibition of PLK1 upregulates E-cadherin and significantly downregulates N-cadherin in SK-MEL-2 melanoma cells." (PMID 38184733, 2024). "The expression of NICD was significantly downregulated after PLK1 knockdown in A375, SK-MEL-2, and WM115 melanoma cells, and upregulated in PLK1 overexpressing and constitutively active PLK1 (T210D) containing A375 and WM115 cells." (PMID 38184733, 2024). "Overall, these results suggest the significance of PLK1, NUMB, and NOTCH signaling in melanoma progression and patient survival." (PMID 38184733, 2024). "Further, we analyzed protein levels of PLK1, NICD (NOTCH intracellular domain), and EMT-related markers in NUMB-modulated melanoma cells." (PMID 38184733, 2024). "To confirm the effects of PLK1 on EMT, we performed a Simple Western analysis of key EMT markers in shNS and shPLK1 harboring A375, WM115, and SK-MEL-2 melanoma cells." (PMID 38184733, 2024). "To determine the clinical relevance of these findings, we conducted immunohistochemistry analysis using melanoma tissue microarray (TMA) and found a strong positive correlation of PLK1 with N-cadherin, a protein required for successful EMT." (PMID 38184733, 2024). "Overall, these results suggest a potential role of PLK1 in EMT, migration, and invasion of melanoma cells." (PMID 38184733, 2024). "In this study, first, using Affymetrix microarray analysis, we demonstrate that shRNA-based PLK1 inhibition modulates EMT and metastasis-related genes and pathways in melanoma cells." (PMID 38184733, 2024). "In summary, combination therapy for melanoma cell progression is an effective therapeutic strategy that can enhance the therapeutic effect by targeting NOD2, TYMS, and PLK1." (PMID 39353904, 2024). "To further explore the potential of the TYMS/PLK1 signaling axis in combination therapy, we have investigated the effects of combining a PLK1 inhibitor (BI6727) with 5-FU or CAP in melanoma." (PMID 39353904, 2024). "Melanoma cells and an in vivo model of sh-NOD2-1, we reconfirmed that NOD2 knockdown upregulated the protein levels of TYMS, PLK1, and p-PLK1." (PMID 39353904, 2024). "PLK1 overexpression (PLK1 OE) in A375, WM115 and SK-MEL-2 melanoma cells enhanced cell proliferation, migration and invasion compared to the empty vector control (pcDNA) cells." (PMID 38184733, 2024). "Our data now provide the first evidence that the whole PLK1 pathway is strongly downregulated after the inhibition of BRAF and EZH2 in resistant melanoma cells." (PMID 36768289, 2023). "Another study revealed that combined inhibition of MEK and mitotic regulator Polo-like kinase 1 (Plk1) resulted in significant growth reduction of NRAS-mutant melanoma cells in vitro and also regression of xenografted NRAS-mutant melanoma in vivo." (PMID 33807778, 2021). "In contrast, mitotic markers PLK1 and FOXM1 were rapidly and consistently reduced in SkMel5 melanoma cells after RGS treatment." (PMID 34092233, 2021). "To investigate the defective ATM checkpoint function produced by dysregulated AURKA- PLK1 pathway, we stably over-expressed wild type AURKA in two ATM checkpoint functional melanoma cells lines, A2058 and A375." (PMID 33993200, 2021). "In melanoma, the downstream kinase targets of CBX7 are Polo-like kinase 1(PLK1) and cyclin-dependent kinase 1(CDK1), which are related to genome stability." (PMID 34659360, 2021). "Polo‐like kinase 1 (Plk1) is a mitotic regulator, which is related to cell cycle regulation, apoptosis and malignant transformation, and overexpression in primary NRAS‐mutant melanoma and melanoma metastases." (PMID 41492362, 2026).